MMP2 (matrix metallopeptidase 2)
Diseases named in the same sentence as MMP2 in open-access papers (continued):
Sharing a sentence is not in itself a finding about the gene and the disease.
squamous cell carcinoma (28 papers, 1999 to 2025). A carcinoma arising from squamous epithelial cells. "In this regard, in some squamous cell carcinoma cell lines, the EMT-specific phenotype was associated with the loss of E-cadherin and induction of vimentin and MMP-2." (PMID 40724562, 2025). "An upregulated expression of MMP-1, MMP-2, and MMP-13 is associated with different malignant pathologies, such as squamous-cell carcinomas of the mouth." (PMID 39596178, 2024). "Overexpression of Snail increases MMP2 expression by binding to its promoter in squamous cell carcinomas." (PMID 37143106, 2023). "In squamous cell carcinoma H1703 cells, at 24 h, MMP-2, MMP-9, TIMP-1, and TIMP-2 in the MG showed higher expression than in the CONT." (PMID 31601869, 2019). "The SIP inhibits proliferation, migration, invasion, and MMP-2 expression of human epidermoid carcinoma cell line KB by inhibiting the EGFR/Akt/p38 MAPK/MMP-2 signalling pathway." (PMID 29597272, 2018). "The positive expression rates of CD147 and MMP-2 in the squamous cell carcinoma and adenocarcinoma among the lung tissues were significantly higher than those in the corresponding normal lung tissues." (PMID 21924036, 2011). "It has been previously demonstrated that Dz13, which downregulates c-Jun, can in fact regulate MMP-2 expression and subsequent activity in endothelial cells and MMP-2 and -9 in squamous cell carcinoma cells." (PMID 20334687, 2010). "Fibroblast-derived HGF/SF has been shown to stimulate invasion and migration in a number of tumour types including squamous cell carcinoma, and we have demonstrated previously that exogenous HGF/SF induces expression of the type IV collagenases MMP-2 and -9 in squamous carcinoma cells." (PMID 14970860, 2004). "There were no statistically significant changes observed in the frequency of the MMP-2-735C/T and MMP-9-1562C/T genotypes between patients with adenocarcinoma, squamous cell carcinoma, and other lung neoplasms." (PMID 37445754, 2023). "In the case of high expression of MMP-2 and MMP-9, both in tumor and its stroma, lower survival rates were demonstrated for squamous cell carcinomas of the tongue and digestive tract." (PMID 31223594, 2019). "In 1998, the results of a study comparing OLP, dysplasia and squamous cell carcinoma (SCC) revealed that MMP-1, MMP-2, and MMP-3 expression were lower in OLP than SCC, and MMPs and TIMPs were clearly upregulated during invasion in oral SCC." (PMID 22737547, 2012). "An expression of MMP-1 (interstitial collagenase), MMP-2 (72-kDa type IV collagenase) and MMP-3 (stromelysin-1) was investigated in squamous cell carcinoma (SCC) and its precancerous condition, actinic keratosis (AK), using in situ hybridization techniques." (PMID 10362121, 1999). "Previous studies have shown that the gene SSB is associated with EMT, and the motility and invasion ability of squamous cell carcinoma cells are decreased after knockdown of SSB, and the expression of matrix metalloproteinase 2 (MMP-2) protein is significantly decreased." (PMID 36785788, 2023). "Assessment of a specific histological subtype, as in the case of MMP2, confirmed this relationship for adenocarcinoma only (p = 0.009), but not for squamous cell carcinoma (p = 0.34)." (PMID 37509417, 2023). "However, the finding that emmprin-CD73 interaction regulates MMP-2 production in co-cultures of tumor cells with fibroblasts has also been confirmed using squamous cell carcinoma cell lines obtained from head and neck tumor (data not shown)." (PMID 31510956, 2019). "During collective cellular migration, which is the predominant pattern adopted by squamous cell carcinoma, MMP1 interacts with integrin α2β1 at the leading edge, and degrades native matrix macromolecules into fragments that are subsequently processed by the gelatinases MMP2 and MMP9." (PMID 24063540, 2013).
squamous cell carcinoma (continued). "Tissue samples from 55 patients with squamous cell carcinoma and adenocarcinoma of the lungs and their corresponding non-cancerous tissues were examined for CD147 and MMP-2 expression using immunohistochemistry." (PMID 21924036, 2011).
Insulin resistance (27 papers, 2012 to 2026). Increased resistance towards insulin, that is, diminished effectiveness of insulin in reducing blood glucose levels. "Secondly, insulin resistance has been linked to heightened activity of MMPs, especially MMP‐2 and MMP‐9, which break down elastin and collagen in the aortic extracellular matrix, resulting in structural weakening and increased risk of dilation." (PMID 41499559, 2026). "Elevated levels of MMP2 expression are associated with insulin resistance due to extracellular matrix (ECM) remodelling in skeletal muscle." (PMID 35692879, 2022). "The negative correlation between TNF-α and MMP-2 activity among T2D patients detected here may implicate that increased insulin resistance is associated with reduced MMP-2 activity." (PMID 34821696, 2021). "The emergence of insulin resistance, associated with decreased vascular reactivity and lowered activity of MMP-2, which leads to vascular collagen accumulation and changes in elastic fibers in the aorta, may be involved in the elevation of SBP caused by OVX." (PMID 30133537, 2018). "In this study, we examined associations between MMP-2 -1306 C/T (rs243865) and MMP-9 -1562 C/T (rs3918242) single-nucleotide polymorphisms, serum levels of MMP-2, MMP-9 and TIMP-1, and the occurrence of insulin resistance in patients in a Polish cohort." (PMID 41828387, 2026). "The role of MMP9 (and MMP2) in sucrose diet-induced insulin resistance needs to be studied in more detail." (PMID 37445827, 2023). "HFD-induced TGF-β/Gbb signaling provokes insulin resistance by increasing tribbles expression and elevating MMP-2 levels in the skeletal muscles of C57BL/6J mice." (PMID 36300928, 2022). "Furthermore, AFM, GSN, CFH, HGFAC, MMP2, and MMP9 have been previously associated with NAFLD or NAFLD-related factors such as liver damage, insulin resistance, metabolic syndromes, and extracellular homeostasis." (PMID 38034020, 2023). "Among them, MMP-2, MMP-9, and MMP-14 are particularly important due to their links with systemic inflammation, insulin resistance, and vascular complications." (PMID 41227041, 2025). "IL-6 upregulates MMP-2 and MMP-9 expression, linking inflammation to vascular remodeling and insulin resistance." (PMID 41227041, 2025). "It has been demonstrated that diet-induced insulin resistance in rats increases MMP-2 arteriolar activity, a process that was reversed by doxycycline, a blocker of the activity site of MMP-2." (PMID 35735622, 2022). "Other study demonstrated that MMP-2 and MMP-9 activity in VSC adipose tissue was decreased in an animal model of early insulin resistance." (PMID 26599360, 2015). "MMP2 and MMP9 are regulated by tissue inhibitors, pro-inflammatory cytokines and other factors such as oxLDL or situations of insulin resistance, where the oxidative stress is increased, and they have both pro- and anti-inflammatory actions." (PMID 22828168, 2012). "Blood samples were collected before and after training, and subjects were tested for changes in clinical parameters, insulin resistance indices [fasting insulin, homeostatic model assessment insulin resistance (HOMA-IR)], MMP-2 and -9, and hydroxyproline, and muscle strength (12-RM), respectively." (PMID 39029066, 2024). "Of note, in a mouse model of sucrose diet-induced insulin resistance, there was reduced AT expression and activity of MMP9 (and MMP2), with no change in MMP circulating levels nor in PPARγ expression." (PMID 37445827, 2023). "In contrast, a decrease in MMP-2 and MMP-9 activity in AT from an animal model of early insulin-resistance (IR) induced by a sucrose-rich diet, without changes in MMPs plasma activity, has been reported." (PMID 30769840, 2019).
type 2 diabetes (27 papers, 2011 to 2026). "Research on the connection of the MMP-2 polymorphism and the incidence of type 2 diabetes is one publication in which the authors focus on the −1306 C/T (rs243865) and −1575 G/A (rs243866) polymorphisms (rs243866) as well as rs2285053 (−735 C/T) and rs9923304." (PMID 36142480, 2022). "The studies reported two single-nucleotide polymorphisms of the promoter of the MMP-2 gene, −1306 C/T (rs243865) and −1575 G/A (rs243866), as those that may be associated with the risk of developing type 2 diabetes." (PMID 36142480, 2022). "MMP2 was associated with extracellular matrix (ECM) receptor interaction, and high AGTR2 expression correlated with Type II diabetes mellitus pathways." (PMID 40995593, 2025). "Evidence from the CECSID trial has shown that miR22-3p downregulation ameliorates visceral adiposity and miR122-5p overexpression affects the extracellular matrix through MMP-2 modulation in Type 2 Diabetes patients." (PMID 36147570, 2022). "In the direct case of type 2 diabetes, the previous reports mention two enzymes from this family: MMP-2 and MMP-9." (PMID 36142480, 2022). "In line with that, physical exercise has a positive effect on ECM remodeling in patients with diabetes type 2 by influencing expression of MMP-2 and its tissue inhibitor TIMP-2." (PMID 31108840, 2019). "The principal findings of this study are that two discrete MMP-2 isoforms are induced in kidneys of murine models representative of Type 1 and Type 2 diabetes." (PMID 30253743, 2018). "Two isoforms of MMP-2 are consistently highly inducible in murine models representative of type 1 and type 2 diabetes and gradually become abundant over time of the diabetic milieu." (PMID 30253743, 2018). "In case of mice with type 2 diabetes (Db/Db vs. Db/Dm), we report a significant 0.56 (±0.32) fold decrease of activity of active form of MMP-2 in comparison to the respective controls (pval < 0.05)." (PMID 29123184, 2017). "Systemic concentrations of MMP‐2 and MMP‐9 are increased in people with type 2 diabetes and peripheral arterial disease." (PMID 33855203, 2021). "Increased plasma MMP-2 and MMP-9 has also been demonstrated in persons with type 2 diabetes and peripheral arterial disease." (PMID 22363890, 2011). "Thus, as shown in our study, the reduction of MMP2 and MMP9 may be a possible mechanism in preventing macrovascular complications in patients with type 2 diabetes by sitagliptin treatment." (PMID 22493727, 2012).
Alzheimer disease (26 papers, 2011 to 2025). A progressive, neurodegenerative disease characterized by loss of function and death of nerve cells in several areas of the brain leading to loss of cognitive function such as memory and language. "The same MMP2 promoter polymorphisms have been associated with increased susceptibility to Alzheimer’s disease, vascular dementia, and Parkinson’s disease, likely due to enhanced transcriptional activity and blood–brain barrier permeability." (PMID 41464177, 2025). "A case-control study was carried out to elucidate the association of MMP2 gene candidate polymorphisms with the susceptibility to Alzheimer’s disease (AD) in the Chinese Han population." (PMID 39456746, 2024). "First, the relatively small size of both groups may reduce the probability of detecting associations between MMP2 variants in the promoter sequences and the risk of late-onset Alzheimer’s disease." (PMID 37109410, 2023). "Thus, MMP2 rs243866 variant seems to be one of the possible determinants of age of Alzheimer’s disease onset." (PMID 37109410, 2023). "The first objective of the current investigation was to assess the association of MMP2 rs243866 (−1575 G>A) and rs2285053 (−735 C>T) polymorphisms with disease susceptibility in a group of Slovak patients with late-onset Alzheimer’s disease by a case-control study." (PMID 37109410, 2023). "MMP-2 and MMP-9 are linked to neuroinflammation and neurodegenerative diseases such as Alzheimer’s disease (AD) and multiple sclerosis as well." (PMID 38069361, 2023). "In a 5xFAD mouse model, MMP-2 upregulation was shown in areas enriched with Aβ during the early stages of Alzheimer’s disease and continued through the progression of the disease." (PMID 37109410, 2023). "Increased expression of MMP-2 has been observed in astrocytes surrounding Aβ plaques and brain endothelial cells in Alzheimer’s disease patients and a decrease in MMP-2 plasma levels compared to healthy individuals." (PMID 37109410, 2023). "In a Slovakian cohort study, MMP2 rs243865 and MMP3 rs3025058 promoter polymorphisms were shown to impact on the onset of Alzheimer’s disease." (PMID 36232390, 2022). "In human tissue, MMP-9 expression increased already in moderate-stage Alzheimer’s disease, whereas MMP-2 expression increased only in late-stage Alzheimer’s disease." (PMID 36232390, 2022). "In the transgenic 5X FAD mouse model of Alzheimer's disease (AD) the expression of MMP-2, MMP-9, and MT1-MMP was upregulated concomitantly with the tissue inhibitor of MMPs-1 (TIMP-1) and several markers of inflammatory/glial response." (PMID 26733793, 2015). "However, increased MMP-2 expression induced by toxic Aβ1-42 oligomers was associated with the disruption of BBB, causing neuroinflammation, synaptic loss, and Alzheimer’s disease progression." (PMID 37109410, 2023). "In Alzheimer’s disease (AD), MMP-2 might be assumed to have a protective role, and in MS, active MMP-2 was associated with the remission phase of the disease, suggesting a role of this enzyme in the termination of MS neuroinflammation." (PMID 35893290, 2022). "Interestingly, MMPs have been characterized as bifunctional proteins in Alzheimer's disease, with some of them, such as MMP-2 and MMP-9, displaying protective roles during disease progression, while others promote disease evolution." (PMID 32454796, 2020). "Among these enzymes, abnormal expressions or activations of gelatinases, MMP-2 (gelatinase A) and MMP-9 (gelatinase B), were reported to be associated with numerous disease conditions, such as cancer, cardiovascular diseases and Alzheimer's disease." (PMID 28945763, 2017). "While this study focuses on understanding the relationship between MMP-2/-9 and ALS, other neurodegenerative diseases, such as Parkinson’s and Alzheimer’s disease, have also been reported to have elevated levels of various MMPs." (PMID 41009467, 2025).
Alzheimer disease (continued). "Active MMPs, i.e. MMP-2 and − 9, decompose the BM of BBB, and their influences have been demonstrated in several pathological conditions such as Alzheimer’s disease (AD), multiple sclerosis (MS), epilepsy, Parkinson’s disease (PD), stroke, and brain cancers." (PMID 40629391, 2025). "Oleic acid is directly responsible for lowering blood pressure by regulating the structure of lipid membranes and inhibiting the activity of gelatinase A (MMP-2), an enzyme involved in the proliferation of cancer and Alzheimer’s disease." (PMID 39458566, 2024). "Previous studies have uncovered that MMP-2 and TNF-α have important roles in the progression of other diseases, such as Alzheimer’s disease and Parkinson’s disease." (PMID 38429778, 2024). "Studies have found a positive correlation between MMP-2 plasma activity and the Mini-Mental Status Examination (MMSE) score in Alzheimer’s disease patients." (PMID 37109410, 2023). "Note that the Alzheimer disease-presenilin pathway identified as the most enriched by the Panther algorithm is related to ECM remodeling (genes included in the pathway: Mmp9, Mmp8, Mmp2, Mmp13, Mmp12)." (PMID 35386010, 2022). "Further work is now required, with a much larger donor group, to quantify the levels of the MMP2 species, and to evaluate the extent to which dysregulation of the MMP system affects the degradation potential towards β-amyloid in Alzheimer's disease." (PMID 28197357, 2017). "In this paper, we discuss various animal models that suggest that the activation of the gelatinases MMP-2 and MMP-9 is involved in pathogenesis of drug dependence, Alzheimer's disease, and epilepsy." (PMID 22235372, 2011). "FA-induced decreased expression levels of BACE1 and APP and increased expression of MMP2 and MMP9 were found by cellular experiments, and FA may be a potential herbal component for the treatment of Alzheimer’s disease." (PMID 39372201, 2024). "CSF concentrations of MMP-9 decrease, concentrations of MMP-3 increase, whilst neither MMP-2 nor TIMPs show significant changes in Alzheimer’s disease patients." (PMID 36232390, 2022). "When investigating plasma samples, a decrease of MMP-2 and MMP-10, but no change in MMP-9 expression level, was reported in Alzheimer’s disease patients." (PMID 36232390, 2022).